STAT5A (signal transducer and activator of transcription 5A)
Diseases named in the same sentence as STAT5A in open-access papers (continued):
Sharing a sentence is not in itself a finding about the gene and the disease.
breast cancer (continued). "Previous studies have linked STAT5A, also known as mammary gland factor (MGF), to mammary function and its high expression in human breast cancers." (PMID 37475016, 2023). "In breast cancer, the role of STAT5A is complex with a potential dual role in the regulation of malignant mammary epithelium." (PMID 38124049, 2023). "As expected, enforced Notch3 expression up-regulates the expression of STAT5A in cell lines of the luminal subtype of breast cancer, whereas suppressing Notch3 expression inhibits the expression of STAT5A in triple-negative breast cancer cell lines." (PMID 38124049, 2023). "The purpose of the current study is to explore the regulatory mechanism of EMT and metastasis through a Notch3/STAT5A axis in breast cancer." (PMID 38124049, 2023). "Further analysis revealed that STAT5A level in ER + breast cancer patients was higher than that in ER- patients (p = 0.01245)." (PMID 38124049, 2023). "In the early stages of breast cancer, STAT5A has been shown to promote malignant transformation and enhance tumor growth, whereas in established breast cancer, STAT5A is involved in maintaining the differentiation of mammary epithelium." (PMID 38124049, 2023). "It is curious to investigate the regulatory mechanism of abnormal STAT5A in human breast cancer patients and its potential function." (PMID 38124049, 2023). "In the early stage of breast cancer, STAT5A/5B promoted malignant transformation of breast epithelial cells and accelerated tumor growth." (PMID 36524006, 2022). "Both PR and STAT5a are key transcription factors in these pathways and have been shown to be mediators of breast cancer stem cell outgrowth." (PMID 36187116, 2022). "Data from murine breast cancer studies suggested that STAT5A had dual efficacy in malignant mammary epithelial cells." (PMID 36524006, 2022). "Overall, our observations from breast cancer patients compelled us to further investigate the consequences of diminished STAT5A and NMI expression during the process of tumorigenesis and metastasis." (PMID 34078871, 2021). "Patient derived xenograft (PDX) whole cell extract (WCE) samples and established breast cancer cell lines spanning the intrinsic molecular subtypes were probed for STAT5a S726 and S780 phosphorylation." (PMID 34188118, 2021). "In contrast, STAT5A/B transcription factors also known to have oncogenic functions and promote breast cancer progression remained unaffected by DOR activation." (PMID 33465556, 2021). "For example, co-overexpression of Janus kinase 2 and signal transducer and activator of transcription 5a was shown to affect mammary cancer cells via the epithelial–mesenchymal transition-pathway." (PMID 33803354, 2021). "Activated STAT5A is known to promote the differentiation and suppress the invasive features of breast cancer cells." (PMID 34120621, 2021). "Here we identified STAT5a as a chemoresistance inducer that regulates the expression of ABCB1 in breast cancer and can be targeted by pimozide, an FDA-approved psychotropic drug." (PMID 34336684, 2021). "Subsequently, the efficacy of pimozide in inhibiting STAT5a and sensitizing doxorubicin-resistant breast cancer cells was tested." (PMID 34336684, 2021). "The results of our study showed that STAT5a was overexpressed and persistently activated in a chemoresistant breast cancer cell line and upregulated ABCB1 expression by promoting its transcription." (PMID 34336684, 2021). "STAT5a and PRL are both implicated in dysregulating apoptotic machinery in breast cancer cells, which was confirmed in our pathway analysis of the MCF7 STAT5a mutants RNA-seq data 24,45–47." (PMID 34188118, 2021). "Here, we identified STAT5a as a key promoter of doxorubicin (DOX) resistance in breast cancer via upregulation of the expression of ABCB1." (PMID 34336684, 2021). "Pimozide sensitizes breast cancer cells to DOX by suppressing the activation of STAT5a and downregulating ABCB1." (PMID 34336684, 2021).
breast cancer (continued). "While STAT5A is a major driver of mammary development, several key questions relevant to breast cancer, remain to be answered." (PMID 34078871, 2021). "We also identified STAT5a as a therapeutic target for treatment of chemoresistant breast cancer and pimozide as a promising candidate to reduce chemoresistance." (PMID 34336684, 2021). "Taken together, these results suggested that STAT5a conferred DOX resistance to breast cancer cells by regulating the transcription of ABCB1." (PMID 34336684, 2021). "Collectively, these studies provide novel insights into STAT5a activation in breast cancer pathogenesis." (PMID 34188118, 2021). "We verified the function of ABCB1 in chemoresistance in breast cancer cells in our study and proved its regulation by STAT5a." (PMID 34336684, 2021). "Our study established the vital role of STAT5a in chemoresistance in breast cancer and verified the mechanism." (PMID 34336684, 2021). "For example, in T-47D and SK-BR-3 breast cancer cell lines, STAT5a and STAT3 differentially regulated BCL-6 expression, a protein involved in apoptosis." (PMID 32633727, 2020). "In breast cancer, Naa10p inhibited metastasis through binding to the transcription factor, signal transducer and activator of transcription 5a (STAT5a), and decreasing STAT5a-mediated ID1 expression." (PMID 32719332, 2020). "Progesterone downregulates miR-141-3p leading to derepression of signal transducer and activator of transcription 5A (Stat5a), and subsequently to expansion of stem-like breast cancer cells." (PMID 32825530, 2020). "L-dopa was recently reported to suppress cellular growth via down-regulation of prolactin-mediated JAK2/STAT5A in breast cancer cells 50, and carbidopa was reported to be an aryl hydrocarbon receptor agonist and to suppress the growth of pancreatic cancer." (PMID 31598163, 2019). "Both high STAT5a and STAT5b mRNA expression are associated with a favorable OS and PFS in breast cancer patients." (PMID 29326301, 2018). "As an alternative cell survival pathway, STAT5a/b has a pro-tumor effect, via overexpression and activation, in head and neck squamous cell carcinomas, and EGFR has been shown to activate STAT5a/b in breast cancer cell lines." (PMID 29492209, 2018). "Our results indicated that STAT3, STAT4, STAT5a, STAT5b, and STAT6 were significantly associated with favorable OS in breast cancer patients, especially for high pathological grade patients." (PMID 29326301, 2018). "Persistent prolactin receptor signalling has been shown in STAT1-deficient mammary epithelial cells, and this results in the activation of JAK2, STAT3 and STAT5A/5B, and the subsequent development of oestrogen receptor-α-positive mammary tumours." (PMID 29875329, 2018). "Downregulation of STAT3 and STAT5a/b has been suggested as a mechanism for anti-proliferative effects of some anti-cancer agents in breast cancer cells." (PMID 30453988, 2018). "It is likely that methylation CpG 12 interferes with binding of STAT5A to its DNA sequence on the FRK promoter hence repressing FRK expression in the breast cancer cells." (PMID 28077797, 2017). "STAT5A’s involvement in many cancers, including prostate cancer, oral squamous cell carcinoma, breast cancer, and colorectal cancer, has been reported." (PMID 28984208, 2017). "STAT5A transactivates the FRK promoter through its putative DNA binding motif, −355/−331.We concluded that in breast cancer cells STAT5A up-regulates the transcriptional expression of FRK." (PMID 28077797, 2017). "Our finding supports that STAT3 was the potential treated target for breast cancer therapy, whereas STAT5A/5B/6 were potential prognostic markers for better survival of BC, providing more accurate prognosis." (PMID 28422733, 2017). "We also analysed STAT5A exon 5 in a separate set of TCGA breast cancer RNA-seq data with tumour-normal-matched pairs." (PMID 27279334, 2016).
breast cancer (continued). "•High levels of STAT5A indicate a good prognosis in breast cancer and it assessment can be used in the clinics as part of a multigene prognostic test." (PMID 27014737, 2016). "For the present validation studies, we analyzed levels of nuclear-localized and tyrosine-phosphorylated Stat5a/b (Nuc-pYStat5) in breast cancer tissue microarray cohorts." (PMID 27312066, 2016). "MiR-141 is negatively regulated in different types of cancers and is considered to be a tumor suppressor, e.g., ovarian cancer, breast cancer, or gastric cancer, by targeting a number of important genes such as p38α, Stat5a, TAZ, and others." (PMID 26790956, 2016). "We exemplify four representative studies showing that STAT5A is generally downregulated in breast cancer." (PMID 27014737, 2016). "All these findings support our data, regarding the involvement of miR-223 and its target STAT5A in both anti-migratory and pro-chemotherapeutic effects and guide us to configure miR-223 as a player of the microenvironment in breast cancer." (PMID 24400121, 2014). "A similar time frame has been described for assessing STAT5A-mediated reporter gene activity of other promoters in breast cancer cells stimulated with a similar concentration of PRL." (PMID 24913037, 2014). "Both STAT5A and STAT5B are key tumor growth stimulators, but STAT5B overexpression seems to be more significant in head and neck and prostate cancers, while STAT5A – in breast cancer." (PMID 25137041, 2014). "Future transcript analyses will focus on further characterizing the differences in gene regulation between Stat5a and Stat5b in human breast cancer." (PMID 23758962, 2013). "In the present study, which focused on PRL-modulated transcripts in the T47D breast cancer model, experimental overexpression of Stat5a or Stat5b enhanced to a comparable extent PRL-modulation of most transcripts tested." (PMID 23758962, 2013). "Seven members of the STAT family have been cloned (STAT1∼4, 5a, 5b, and 6), among which STAT5a and STAT3 were confirmed to be most strongly associated with the proliferation and oncogenesis of human breast cancer cells." (PMID 23554768, 2012). "With selective Stat5a and Stat5b antibodies and immunofluorescence detection on the Automated Quantitative Analysis (AQUA) platform, Stat5a and Stat5b protein levels were quantified in breast cancer progression material." (PMID 23036105, 2012). "Although the new data provide clarity about Stat5a and Stat5b in breast cancer, several limitations of this study exist." (PMID 23036105, 2012). "In MCF-7 human breast cancer cells, expression of selected genes also differed after stable introduction of constitutively active Stat5a or Stat5b." (PMID 23036105, 2012). "Experimental support for a promoting role of Stat5a in mammary tumor initiation includes genetic models in mice in which Stat5a is either suppressed or hyperactivated." (PMID 23036105, 2012). "Stat5a and Stat5b transcript levels in breast cancer were correlated with clinical outcome in 936 patients." (PMID 23036105, 2012). "In contrast, Stat5b protein levels remained unchanged, suggesting divergent expression and involvement of Stat5a and Stat5b during breast cancer progression." (PMID 23036105, 2012). "Collectively, these discrepant and incomplete data warrant a more systematic effort to quantify Stat5a or Stat5b protein expression during human breast cancer progression relative to normal breast tissue." (PMID 23036105, 2012). "Introduction of dominant-negative STAT5a mutants into ER-positive T47D breast cancer cells inhibits estrogen-stimulated cell growth and induces apoptosis." (PMID 22276155, 2012). "Consistent with the notion of distinct roles in human breast cancer, experimental hyperactivation of transcription factors Stat5a or Stat5b independently in MCF-7 breast cancer cells revealed only limited overlap between Stat5a- and Stat5b-responsive genes." (PMID 23036105, 2012).
breast cancer (continued). "For instance, in breast cancer a highly predictive consensus decision module was identified among C/EBPβ, STAT5A, and HSF1 – three genes whose activity has been shown to directly influence cancer progression." (PMID 21980275, 2011). "Stat5a nuclear localization was observed in 76% of breast cancer specimens and a positive correlation was established between its nuclear localization and the level of histological differentiation of the tumors." (PMID 19450255, 2009). "Published accounts vary in the degree of STAT5a positivity reported in human breast cancer, with one study indicating a 17% positivity rate for STAT5a in breast cancers (approximating the rate found in our article), and another demonstrating STAT5a in 76%." (PMID 21655368, 2008). "Moreover, overexpressing STAT5A partially reversed the enhanced mobility of breast cancer cells following Notch3 silencing." (PMID 38124049, 2023). "Previous studies have suggested that STAT5A/5B could regulate the tumor cell proliferation, invasion and metastasis in breast cancer." (PMID 36862902, 2023). "N-α-Acetyltransferase 10 protein (Naa10p), the catalytic subunit of N-acetyltransferase A, inhibits the metastasis of breast cancer cells by binding STAT5A and decreasing STAT5A-stimulated inhibitor of differentiation 1 (ID1) expression in an acetyltransferase-independent manner." (PMID 38124049, 2023). "A possible mechanistic explanation for the association of higher STAT5a with favorable overall survival in breast cancer might be the role of STAT5a in promoting heterochromatin formation." (PMID 37369132, 2023). "Ectopic STAT5A knockdown partially restored the migration and invasion of breast cancer cells, following Notch3 overexpression-induced suppression, indicating that Notch3-mediated inhibition of breast cancer metastasis occurs in part through activating STAT5A expression." (PMID 38124049, 2023). "Moreover, downregulation of prolactin-mediated JAK2/STAT5A signaling by Mucuna pruriens, an ancient Indian medicinal plant enhanced cisplatin efficacy in the treatment of breast cancer cells." (PMID 38124049, 2023). "However, in mouse breast cancer, Stat5a transcriptional increases the secretion of IL-1ra, a traditional immune-suppressive cytokine, which was the downstream of miR-100 to maintain phenotype of tumor-associated macrophages and promote tumor metastasis." (PMID 38124049, 2023). "Further exploration demonstrated that low expression of STAT5A and Notch3 both predict poor survival of breast cancer patients, which may be related to the suppressed immune response." (PMID 38124049, 2023). "Low expression of Notch3 and STAT5A predicted poorer prognosis of patients with breast cancer." (PMID 38124049, 2023). "Interestingly, in most human mammary tumors, miR-221/222 are key breast cancer cell proliferation and invasion regulators and exert their effects via post-transcriptional regulation of STAT5A, and also suppress Notch3." (PMID 38124049, 2023). "Importantly, when compared in different stage of breast cancer, the higher STAT5A expression level, the well differentiation of breast cancer (p < 0.00001)." (PMID 38124049, 2023). "Another study demonstrated that STAT5a may be a promising target to overcome resistance in the breast cancer." (PMID 36980610, 2023). "Meanwhile, current study focused on the tumor suppressor role of STAT5A in luminal and triple-negative subtypes of breast cancer, which is proposed as a novel biomarker for metastasis of breast cancer, evoking the potential therapeutic effect of analogs of STAT5A or N3ICD/STAT5A axis." (PMID 38124049, 2023). "Similarly, in transwell assays, Notch3-mediated inhibition of cell migration and invasion of breast cancer cells was partially reversed by suppressing the Notch3 downstream target STAT5A." (PMID 38124049, 2023). "Besides, NAA10 inhibits the migration and invasion of breast cancer cells by binding to STAT5a and decreases STAT5a‐stimulated ID1 expression." (PMID 35366056, 2022).
breast cancer (continued). "And in the breast cancer clinical sample activated STAT5A/5B was positively correlated with the differentiation status of breast cancer, but it can also prevent the dissemination of confirmed breast cancer, which was a sign of good outcome for breast cancer with negative lymph nodes." (PMID 36524006, 2022). "HOXA1 was found to upregulate the expression of BCL2 in breast cancer, which could also enhance cell proliferation and promote malignant transformation of cancer cells by activating STAT5a/b and MAPK signaling pathways." (PMID 35677036, 2022). "Some studies have found that STAT5A inhibits cell invasion and metastasis in breast cancer." (PMID 35241179, 2022). "Active STAT5A characterizes breast cancer patients for favorable prognosis." (PMID 34078871, 2021). "DNA-damaging agents such as doxorubicin are reported to induce STAT5a expression in breast cancer; however, the exact role of STAT5a in chemoresistance in breast cancer remains unknown." (PMID 34336684, 2021). "Active STAT5A characterizes breast cancer patients with favorable prognosis." (PMID 34078871, 2021). "Subsequently, a rescue experiment was performed to confirm whether STAT5a modulates chemoresistance in breast cancer cells by regulating ABCB1." (PMID 34336684, 2021). "Using siRNA, we silenced STAT5A in MDA-MB-468 breast cancer cells." (PMID 34078871, 2021). "Findings from the study conducted by Dr Rui’s group support the notion that STAT5A signaling is frequently absent during breast cancer progression and loss of nuclear phospho-Stat5 is associated with poor prognosis in node-negative breast cancer." (PMID 34078871, 2021). "STAT5a confers breast cancer chemoresistance by upregulating the transcription of ABCB1." (PMID 34336684, 2021). "Candidate pathways were constructed starting from the estrogen receptor ESR1 gene and targeting breast cancer-associated transcription factors, such as JUN, FOS, STAT1, STAT3, STAT5A, ELK1, and ETS1 (Target transcription factors were pre-identified by GibbsOS19)." (PMID 33432018, 2021). "Given hematopoiesis studies showing phospho-serine STAT5a as necessary for transformation, we hypothesized that serine phosphorylation regulates STAT5a activity to contribute to its role in mammary oncogenesis, specifically in luminal breast cancer." (PMID 34188118, 2021). "Finally, we verified the role of STAT5a in doxorubicin resistance in breast cancer and the efficacy of pimozide in reversing this resistance in vivo." (PMID 34336684, 2021). "Breast cancer specimens with high STAT5a expression showed high ABCB1 expression levels." (PMID 34336684, 2021). "Further, it was observed that the T47D breast cancer cell line, when either transiently transfected or stably transduced with the STAT5a rescue constructs, had variable success in establishing 2D colonies; ultimately only transient expression was viable for performing quantitative assays." (PMID 34188118, 2021). "Our study demonstrated the vital role of STAT5a in doxorubicin resistance in breast cancer." (PMID 34336684, 2021). "Data mining based on GSE87455 was conducted to explore whether STAT5a is involved in chemoresistance in breast cancer." (PMID 34336684, 2021). "A recent study also demonstrated high siRNA uptake, marked reduction of STAT5A mRNA levels as well as increase in cell death using lipid-modified PEIs in breast cancer cell lines, which is consistent with our findings here and supports the efficacy of our delivery system." (PMID 34157051, 2021). "Together, these results illustrate that STAT5a expression restricts the extent of breast cancer outgrowth and clonogenicity, and that loss of any individual phospho-regulatory site on STAT5a does not mimic total loss of STAT5a44." (PMID 34188118, 2021).